CRP (C-reactive protein)
Diseases named in the same sentence as CRP in open-access papers (continued):
Sharing a sentence is not in itself a finding about the gene and the disease.
endometrial cancer (33 papers, 2010 to 2025). Primary or metastatic malignant neoplasm involving the endometrium (mucous membrane that lines the endometrial cavity). "Multivariable analysis further confirmed that the protective association between SLE and endometrial cancer remained significant after controlling for BMI, estradiol, and CRP (OR = 0.96, 95% CI [0.93–0.99], p = 0.014)." (PMID 40406544, 2025). "The analysis assesses the direct effect of SLE on endometrial cancer risk while controlling for the potential confounding effects of BMI, estradiol, and CRP." (PMID 40406544, 2025). "Recently, CRP has been considered as a diagnostic and prognostic factor in the development of endometrial cancer." (PMID 38397036, 2024). "A significant increase in risk of endometrial cancer was observed with elevated levels of C-reactive protein, interleukin 6 (IL-6), and interleukin 1 receptor antagonist (IL-1Ra)." (PMID 37175971, 2023). "Another small study of just 110 women with endometrial cancer demonstrated an association between pre-treatment CRP levels and both overall and disease-free survival." (PMID 34802721, 2022). "Immunological factors such as TNF-α, TNF receptors 1 and 2, IL-6, and C-reactive protein (CRP) have been identified as inflammatory variables associated with an increased risk of endometrial cancer in postmenopausal women." (PMID 35628566, 2022). "CRP is a simple, easy to perform, low-cost test that can aid the identification of women at a higher risk of death from endometrial cancer." (PMID 34802721, 2022). "•CRP offers a simple, low-cost endometrial cancer prognostic test with potential to refine pre-treatment risk assessment." (PMID 34802721, 2022). "As independent risk factors in this analysis, CRP and D-D concentrations prompted a new prognostic hierarchy where stipulated subsets better reflected actual outcomes of patients with endometrial cancer." (PMID 26107255, 2015). "In particular elevated CRP serum levels have been associated with impaired survival in patients suffering from gynaecologic malignancies including cervical, ovarian, and endometrial cancer." (PMID 26248232, 2015). "To further control for potential confounding factors, we conducted a multivariable genetic association analysis to assess the direct effect of SLE on the risk of developing endometrial cancer, while considering potential confounders such as BMI, estradiol, and CRP." (PMID 40406544, 2025). "As part of the conducted case–control study, an attempt was made to establish the relationship between CRP, IL-6, IL-1RA (interleukin 1 receptor antagonist), and the degree to which these variables are associated with the risk of obesity and endometrial cancer." (PMID 35628566, 2022). "If confirmed in an independent cohort, CRP may offer a simple, low-cost test to refine pre-treatment risk assessment and guide personalised care in endometrial cancer." (PMID 34802721, 2022). "A limited number of studies have examined the relationship between inflammatory biomarkers and endometrial cancer survivors; nevertheless, findings have consistently demonstrated an inverse association between circulating levels of CRP and endometrial cancer survival." (PMID 35174651, 2022). "In addition, another report showed that elevated pre-therapeutic CRP serum levels were associated with less favourable prognosis in patients with surgically treated endometrial cancer." (PMID 26248232, 2015). "If validated in an independent cohort, CRP could provide a simple, low-cost prognostic test that has the potential to refine pre-treatment risk assessment and guide decisions about adjuvant treatment in endometrial cancer." (PMID 34802721, 2022). "The study demonstrated an association between the presence of TNF-α, TNF receptors 1 and 2, IL-6, and C-reactive protein (CRP) and an increased risk for endometrial cancer in postmenopausal women." (PMID 41050662, 2025).
endometrial cancer (continued). "Consensus remains elusive regarding the relationship between C-reactive protein (CRP) levels and endometrial cancer (EC)." (PMID 39809220, 2024). "Here, we show that CRP is a strong predictor of endometrial cancer survival outcomes following robust adjustment for important clinico-pathological confounders." (PMID 34802721, 2022). "The potential prognostic utility of CRP has been investigated in many solid malignancies, although endometrial cancer has been relatively understudied." (PMID 34802721, 2022). "A systematic review found CRP was prognostic in 90% of the 271 included studies, but few assessed its utility in the context of endometrial cancer." (PMID 34802721, 2022). "In this study, we found pre-treatment CRP to be an independent prognostic biomarker in endometrial cancer." (PMID 34802721, 2022). "Here, we show evidence for the potential utility of CRP as a prognostic biomarker in endometrial cancer." (PMID 34802721, 2022). "In detail, three large case studies demonstrated a relationship between the circulating levels of TNF-α, IL-6, IL-1α, and C-reactive protein (CRP) and elevated risk of endometrial cancer." (PMID 35053431, 2022). "Serum levels of C-reactive protein (CRP), IL-6, and IL-1 receptor antagonist (IL-1Ra) are significantly associated with endometrial cancer risk when analyzing 246,000 women in ten European countries." (PMID 32363546, 2020). "C-peptide, insulin, C-reactive protein, leptin, IL-1Ralpha, and IL-6 decreased significantly, while SHBG, IGFBP1, and adiponectin increased significantly in weight-loss interventions in endometrial cancer." (PMID 31440472, 2019). "In the EPIC study and in the Women’s Health Initiative, C-reactive protein (CRP) and other pro-inflammatory cytokines (such as IL1 receptor antagonist) were found to be positively associated with endometrial cancer." (PMID 29132343, 2017). "In this study, both CRP and D-D concentrations were identified in multivariate analyses as independent prognostic variables for survival in patients with endometrial cancer." (PMID 26107255, 2015). "In patients with Type II endometrial carcinoma, higher concentrations (P<0.01) of CRP, PLR and NLR were observed." (PMID 26107255, 2015). "Only limited data exist on prognostic serum tumour markers in patients with endometrial cancer, such as CA 125 and C-reactive protein." (PMID 20160724, 2010). "Consistently with our findings, another paper reported that endometrial cancer patients had increased levels of oxidative stress markers, in comparison to controls, and that they were associated with increased values of circulating TNF-α, IL-6, and CRP." (PMID 35053431, 2022). "Studies of the association between the pro‐inflammatory cytokine C‐reactive protein (CRP) with endometrial cancer incidence have been mixed, and meta‐analyses of tumor necrosis factor alpha (TNF‐α) and interleukin 6 (IL‐6) have not demonstrated an association with endometrial cancer risk." (PMID 35174651, 2022). "For endometrial cancer, there was positive mediating effect through estradiol, while with less certainty, the estimates were also indicative of possible mediating effects through insulin, and leptin and CRP." (PMID 35048536, 2022). "For plasma proteins, a six-biomarker panel combining SERPINA4, APOA2, TTR, CRP, CLEC3B and APOD predicted advanced stage endometrial cancer with AUC 0.93 (0.85–0.99)." (PMID 38513301, 2024). "All serum biomarkers assessed (CA125, CA15-3, CRP, D-D, PLR, and NLR) proved to be valid prognostic indices of surgically treated endometrial cancer." (PMID 26107255, 2015). "Similarly, reverse causation could explain the previously reported associations between CRP, a nonspecific indicator of inflammation, and endometrial cancer risk, as early stages of endometrial carcinogenesis may induce an inflammatory response, leading to elevated levels of CRP." (PMID 35436960, 2022).
endometrial cancer (continued). "Importantly, this association remained significant after controlling for BMI, estradiol, and CRP, indicating that the negative association between SLE and endometrial cancer is independent of these factors." (PMID 40406544, 2025). "Following adjustment for age, BMI, FIGO stage, disease grade, histology, LVSI, depth of myometrial invasion and baseline CRP, those with T2DM had a two-fold increase in the risk of death from endometrial cancer compared to those without (adjusted HR 2.15, 95% CI 1.05-4.39), p=0.035)." (PMID 35600348, 2022). "Many systemic inflammatory markers such as serum C-reactive protein (CRP), neutrophil-lymphocyte ratio (NLR), or platelet-lymphocyte ratio (PLR) have been shown to be a prognostic marker in various kinds of human cancers such as lung, colorectal, ovarian, and endometrial cancer." (PMID 30631798, 2018).
essential hypertension (33 papers, 2007 to 2025). Hypertension that presents without an identifiable cause. "Chronic catecholamine excess in patients is associated with significantly increased levels of inflammatory markers (white blood cells, platelets, and CRP), which are significantly higher than those in patients with primary hypertension and aldosteronism." (PMID 38669419, 2024). "Elevated CRP has also been described by other authors in children with primary hypertension." (PMID 40869561, 2025). "Clinical data demonstrated that inflammatory biomarkers such as CRP, IL-6, and TNF-α significantly increased in primary hypertension, and this increase is observed significantly more often in nondippers and is associated with the onset of target organ damage and cardiovascular events." (PMID 28757677, 2017).
Hypoglycemia (33 papers, 2008 to 2025). A decreased concentration of glucose in the blood. "Hypoglycemia also induces the production of several inflammatory markers, including interleukin(lL)-6, C-reactive protein, TNFα, IL-8, and endothelin-1, which can cause endothelial injury." (PMID 30813549, 2019). "Laboratory testing showed hypoglycemia, multiple pituitary hormonal deficiencies, and an elevated C-reactive protein level." (PMID 28588003, 2017). "In addition, hypoglycemia may also cause kidney injury by elevating the C-reactive protein and pro-inflammatory cytokine levels." (PMID 40870371, 2025). "We have previously reported that inflammatory regulators are increased at the time of hypoglycemia, are exaggerated in T2D, and that all apart from C-reactive protein return to normal at 24 h." (PMID 34831332, 2021). "Blood pressure (4 reviews), serum lipid/cholesterol levels (4 reviews), waist circumference, severe hypoglycemia/adverse effects (1 review), and C-reactive protein level (1 review) were also explored." (PMID 32343253, 2020). "Inflammatory regulators were increased at the time of hypoglycemia and, despite returning to normal at 24 hours, there was a residual effect on inflammation as seen by the increase in the inflammatory marker CRP." (PMID 32179763, 2020). "VIG group demonstrated significant decrease in HbA1c, diastolic blood pressure, frequency of hypoglycemia, and high-sensitivity C-reactive protein level as compared to the changes in control group." (PMID 32267348, 2020). "Initial laboratory results demonstrated a normal white blood cell count, an elevated serum CRP, and hypoglycemia in our patient, which together with the elevated body temperature was initially considered highly suggestive of pituitary abscess." (PMID 28588003, 2017). "The quantitative analyses revealed that only one protein, C-reactive protein, was up-regulated in hypoglycemia groups." (PMID 28529466, 2017). "At 24 hours of age neonates with hypoglycaemia ≤ 2.55 mmol/L together with CRP values > 1.35 mg/L or those with BW ≤ 678 g had more than 30% likelihood of treatment failure." (PMID 19930706, 2009). "The principal discriminator was hypoglycaemia ≤ 2.55 mmol/L which was followed by CRP values > 1.35 mg/L in infants with hypoglycaemia and by BW ≤ 678 g in those without." (PMID 19930706, 2009). "The polysaccharide active ingredients in ES significantly mitigated the alterations in glucose and C-reactive protein (CRP) levels caused by alcohol, thereby reducing the severity of alcohol hangover through inhibition of alcohol-induced hypoglycemia and neuronal inflammatory responses." (PMID 41048351, 2025). "Two Newborns with intrapartum asphyxia had hypoglycemia (RBS < 2.5Mmol/l), and infection (CRP > 10 mg/dl)." (PMID 29556412, 2018). "Increased levels of C-reactive protein (CRP), IL-6, IL-8, TNF-α, and endothelin-1 have been shown during hypoglycemia." (PMID 28115020, 2017). "Initial laboratory results demonstrated a normal white blood cell count (9.2x109 /L; 54% neutrophils), an elevated serum C-reactive protein (CRP) (201 mg/L) and hypoglycemia (2.8 mmol/L)." (PMID 28588003, 2017). "Along with the drive of the sympathoadrenal activation, several inflammatory markers including C-Reactive Protein (CRP), Interleukin 6 (IL-6), Interleukin 8 (IL-8), Tumor Necrosis Factor α (TNF-α), and endothelin-1, have been shown to be increased during hypoglycemia." (PMID 34572493, 2021). "In non-DM patients, plasma C-reactive protein concentrations was higher in patients with hypoglycemia than in those without hypoglycemia (0.064 ± 0.013 mg/dL vs. 0.107 ± 0.051 mg/dL, respectively)." (PMID 28789689, 2017). "When the clinical symptoms or signs were compared, significantly more patients in the high CRP group had apnea, bradycardia with or without cyanosis, feeding intolerance, hyper- or hypoglycemia, or septic shock compared to those in the low CRP group." (PMID 26259626, 2015).
Hypoglycemia (continued). "The relationship between hypoglycemia in T2DM and cardiovascular outcome was independent of traditional CV risk factors and the value of several biomarkers, including high-sensitivity troponin T, NT-proBNP, and C-reactive protein." (PMID 36271363, 2022).
mental disorder (33 papers, 2017 to 2026). A disease that has its basis in the disruption of mental process. "Third, we investigated possible associations between CRP and many risk factors for various complex diseases including CVDs, mental disorders, and neoplasms as well as other diseases." (PMID 36376304, 2022). "Severe mental disorders such as schizophrenia, bipolar disorder and depression have been associated with higher levels of CRP." (PMID 35243104, 2022). "There is some evidence to suggest antenatal CRP levels are associated with pregnancy-related complications, mental disorders in offspring, infant birthweight, and neonatal CRP levels." (PMID 32722722, 2020). "Inflammatory factors, such as IL-6 and CRP, may also have the potential to serve as early warning indicators for air pollution-related risk of mental disorders." (PMID 39058106, 2024). "Research has shown that patients with catatonia have significantly higher levels of C-reactive protein (CRP) compared to patients with other mental disorders, suggesting a clear association between catatonia and inflammation, not solely due to changes in psychopathology or stress levels." (PMID 39398953, 2024). "Inflammatory processes may be linked to suicidality, and increased CRP levels are associated with mortality risk in people with mental disorders." (PMID 32219505, 2020). "Several studies have shown a significant association between C-reactive protein (CRP) levels and the development of mental disorders, suggesting this marker can be used as a screening tool for the progression of the disease." (PMID 37803327, 2023). "However, accumulating evidence suggests that mental disorders are associated with elevated levels of inflammatory biomarkers, such as interleukin-6 (IL-6), tumor necrosis factor-alpha (TNF-α), and C-reactive protein (CRP)." (PMID 41019538, 2025). "The present findings could be relevant for developing new therapeutic approaches and enhancing our understanding of inflammatory biomarkers in mental disorders, positioning CRP as a possible biomarker for mental disorders." (PMID 39452916, 2024). "Elevated CRP concentrations in the central nervous system may promote inflammatory responses, potentially leading to the development of mental disorders." (PMID 39452916, 2024). "Therefore, further research to understand and compare the potential distinct role of IL‐6 and CRP in the development of mental disorders is needed." (PMID 36597271, 2023). "Although the risk has not been tied to polygenic CRP, blood CRP level has been found to be strongly associated with a history of mental disorders." (PMID 37860004, 2023). "Possible mechanisms underlying the interactions between CRP and mtDNA for mental disorders are not fully clarified." (PMID 37344456, 2023). "CRP; Aging; Inflammation; Psychiatry; Immune markers; Emergency psychiatry; Mental disorders." (PMID 35243104, 2022). "High sensitivity (hs)-CRP is a more sensitive test for subtle inflammation, and serum hs-CRP may reflect a low-grade systemic inflammatory state of various mental disorders." (PMID 35114967, 2022). "We recorded each participant's age, gender, educational level, smoking, marital status, family history of mental disorder, military service, age at diagnosis of SCZ, and baseline ESR and CRP levels." (PMID 30618856, 2018). "Unlike other mental disorders, the exact neurological mechanisms of DEACMP remain elusive; nonetheless, several risk indicators have been identified, such as abnormalities in cranial CT/MRI scans, C-reactive protein levels." (PMID 40821012, 2025). "Our review suggests that several oxidative stress and inflammatory biomarkers, such as peripheral TAC, IL-17, IL-6, and CRP, may be possible non-specific early warning indicators for air pollution-related development or progressive aggravation in mental disorders." (PMID 39058106, 2024).
mental disorder (continued). "Although casualty has not been proven, high C-reactive protein (CRP) and interleukin 6 (IL-6) concentration are reported in mental disorders." (PMID 34465310, 2021).
Sjögren’s syndrome (33 papers, 2014 to 2025). "Interestingly, a post‐COVID‐19 syndrome in patients with primary Sjögren's syndrome has a frequency of nearly 60% and is associated with hospitalization, baseline CRP levels, and hydroxychloroquine levels, but worsened sicca symptoms were not reported." (PMID 39021490, 2024). "Inflammatory myopathies, primary Sjögren’s syndrome and systemic sclerosis are other diseases for which CRP is considered an unreliable marker for monitoring disease activity." (PMID 34945133, 2021). "Laboratory evaluation should include a CBC with differential, erythrocyte sedimentation rate, c-reactive protein, antinuclear antibodies, angiotensin converting enzyme, anti-Sjogren’s syndrome A and B antibodies, rheumatoid factor, and immunoglobulin G antibodies with immunoglobulin G-4 ratio." (PMID 37723320, 2023). "Their expression was strongly related to the ESSDAI (EULAR Sjögren’s syndrome disease activity index) score and the serum IgG, CRP (C-reactive protein), and C4 levels, which were closely correlated with the disease activity of pSS." (PMID 35796900, 2022). "However, in our hands, sera from patients with RA or inflammatory bowel disease have consistently been negative in the anti-CRP assay, whereas a few additional patients with primary Sjögren’s syndrome and chronic hepatitis C infection tested positive." (PMID 34945133, 2021). "While CRP is not a good marker for disease activity in primary Sjögren's syndrome, a prospective study assessing clinical and laboratory manifestations as well as ESSDAI at diagnosis and follow‐up would improve the understanding of disease‐related risk factors." (PMID 31127862, 2019).